MACC1 (MET transcriptional regulator MACC1)
Diseases named in the same sentence as MACC1 in open-access papers (continued):
Sharing a sentence is not in itself a finding about the gene and the disease.
tumor (continued). "First, we stained MACC1 and S100P protein levels in tumour sections of CRC patients without synchronous metastasis at the time of diagnosis (UICC I–III) by IHC." (PMID 35597866, 2022). "The results of this experiment showed that MACC1 could activate the HGF and then stimulate the phosphorylation of c-MET, thus enhancing the invasion ability of tumor cells." (PMID 35874635, 2022). "MACC1 upregulation resulted in decreased epithelial markers such as E­cadherin and increased mesenchymal markers such as vimentin in certain cancers, thus promoting EMT, tumor invasion and metastasis." (PMID 33854976, 2021). "Despite the manifold pro-metastatic activities of MACC1, its impact on platelet activation and interaction by the respective tumor cells has not yet been investigated." (PMID 34830078, 2021). "Driving the β-catenin/Wnt pathway and EMT is an emerging similarity shared by IGFPB2 and MACC1 in fostering tumor malignancy; however, both have not been functionally related yet." (PMID 34830078, 2021). "In addition, MACC1, E-cadherin and vimentin levels were correlated with cancer staging and TNM tumor classification." (PMID 33854976, 2021). "Although the direct activation of c-Met/Akt via MACC1 was not addressed in that study, it is regulated by MACC1 in many tumor types." (PMID 32503676, 2020). "Expression of the MACC1 gene, particularly in CRC, can result in tumor invasion and metastasis." (PMID 32670264, 2020). "In CRC patients, it has been found that tumor lesion MACC1 expression significantly increased in relation to its non-tumorous adjacent tissues." (PMID 30805302, 2019). "From this discovery and previous research, we wondered whether there was a correlation between MACC1 and PDL1 and what role MACC1 plays in tumor immune evasion." (PMID 31557409, 2019). "From these data, we infer that MACC1 regulates PDL1 expression and tumor immunity through the c‐Met/AKT/mTOR pathway in GC cells and suggest that MACC1 may be a therapeutic target for GC immunotherapy." (PMID 31557409, 2019). "Furthermore, when MKN28 cells overexpressing MACC1 were treated with the PDL1 inhibitor, the tumor cell killing rates of the vector‐NC and MACC1 groups were significantly higher than those of the untreated vector‐NC and MACC1 groups (P < .05)." (PMID 31557409, 2019). "However, this increase did neither correlate with debulking efficiency nor with residual tumor burden or prognosis, suggesting that this phenomenon could be caused by an unspecific and transient release of MACC1 and S100A4 mRNA into the blood, possibly due to tissue damage during surgery." (PMID 30927479, 2019). "Interestingly, many of these genes are known to be involved in cell-cycle function (CDK2, CDK6, CCNB1, CEP55, CENPF), transcriptional regulation/tumor suppression (FOXO3, TOP2A), DNA-damage response (ASPM, XRCC4), and tumor progression (CYR61, MACC1, CXCR4)." (PMID 28482906, 2017). "Overall, studies of VM, ALDH1, KiSS-1, and MACC1 in association with tumor metastasis and prognosis suggest that these factors affect cancer progression; however, the associations among VM, ALDH1, KiSS-1, and MACC1 in EOC has not been widely reported." (PMID 28253891, 2017). "In previous studies, the MACC1 expression was not tumor-stage dependent which supports our findings." (PMID 27462788, 2016). "Our data showed that serum MACC1 levels were associated with clinical TNM stage, tumor size, lymph node status and Ki-67 status, but not ER and HER2 status, which are universally acknowledged as important BC prognostic biomarkers." (PMID 27793048, 2016). "In addition, we found that the nuclear expression of MACC1, TWIST1, and TWIST2 proteins was significantly higher in the tumor tissues of VM-positive GC patients than in their matched adjacent non-tumor tissues (p = 0.045, p = 0.015, and p = 0.007)." (PMID 25895023, 2015).
tumor (continued). "Patients with strong MACC1 expression in the tumor center frequently presented with locally advanced pT3/4 tumors (p = 0.0288) as compared to MACC1 negative cases." (PMID 25884643, 2015). "Moreover, nuclear expression of MACC1, TWIST1, and TWIST2 was upregulated in GC tissues compared with matched adjacent non-tumorous tissues (p < 0.05)." (PMID 25895023, 2015). "For MACC1, there were significant differences in levels of expression between tumor tissues (Mean ± SD, 145.37 ± 289.74), non-tumor tissues (Mean ± SD, 69.13 ± 158.41), and inflammatory tissues (Mean ± SD, 10.04 ± 6.12) (Kruskal–Wallis test; p < 0.05)." (PMID 24934327, 2015). "Independent of geographic location, MACC1 predicted advanced pT and pN-stages, high grade tumor budding, venous and lymphatic invasion (p < 0.05)." (PMID 25884643, 2015). "To determine whether MACC1 affects the tumorigenicity of CRC cells in vivo, we performed tumor growth experiments in nude mice." (PMID 25003996, 2014). "In our validation cohort, early-stage (TNM stages I-II, tumor size less than 3 cm, single tumor nodule) HCC patients with high level of MACC1 protein immunostained also display a relative low OS than those diagnosed with late-stage HCC who carry high levels of MACC1 expression." (PMID 23717574, 2013). "We observed no significant variations of MACC1 levels due to age, sex, or between the tumor stages I, II and III." (PMID 23166620, 2012). "Moreover, stratified analysis showed that tumour-node-metastasis (TNM) stage I patients with high MACC1 levels had shorter OS and DFS than those with low MACC1." (PMID 21955323, 2011). "Additionally, there was inconsistency in the expression of MACC1 and NELL2, which may be due to the high heterogeneity of tumor tissues from different sources." (PMID 38818465, 2024). "For example, MACC1 promotes the epithelial-mesenchymal transition (EMT) process by binding to SNAIL that mediates apoptosis through STAT1/3 and Akt/β-catenin signaling pathway and induces tumor growth against metabolic stress by facilitating the Warburg effect." (PMID 39695175, 2024). "Indeed, there are several biological features supporting the MACC1-LGR5 link, i.e., the involvement of MACC1 and of LGR5 in clathrin-mediated endocytosis, their localization at the tumor invasion front, their role in core clock regulation and their impact on craniofacial development." (PMID 38339354, 2024). "Neither the tumor grade, clinical stage, lymph node involvement, PR status, histological type (ductal versus lobular BC), patient age, or overall survival were shown to be substantially correlated with MACC1 expression." (PMID 36979146, 2023). "Furthermore, it also appears necessary to elucidate the MACC1-dependent effects on changes in the adhesive system, currently summarized under the broad term EMT, as they largely determine collective migration, a key factor in tumor invasion." (PMID 37051546, 2023). "MACC1 binds to the positive feedback of the c-Met promoter region to activate the HGF/c-Met pathway, upregulates the expression of downstream target cyclin D1, and promotes tumor cell proliferation, invasion, metastasis, and epithelial mesenchymal transformation (EMT)." (PMID 35242498, 2022). "Previous studies demonstrated that MACC1 can regulate the expression of the oncogene c-MET and promote epithelial-mesenchymal transformation, migration, proliferation, angiogenesis, and drug resistance in various tumor cells through the HGF/c-MET/MAPK and HGF/c-MET/AKT pathways." (PMID 35874635, 2022). "We showed next by using the TCGA COAD-READ cohort, that increased MACC1 SCNA and expression occurred in tumors with chromosomal instability (CIN molecular subtype) for which CRC patients have, in general, a less favorable outcome compared to MSI or GS tumor subtypes." (PMID 35406521, 2022).
tumor (continued). "Similarly, it was reported that miR-940 could reversely regulate CKS1, MACC1, MTHFD2 and SPOCK1 in tumors, indicating its significant function in tumor occurrence and development." (PMID 35297315, 2022). "Notably, deregulation of MACC1 or IGFBP2 did not affect tumor-cell-induced thrombin formation, which is considered of overriding importance for tumor-related thrombosis and metastasis." (PMID 34830078, 2021). "Thus, MACC1 might affect immune cells infiltration in the TME and enhance tumor cells immune escape." (PMID 34577857, 2021). "However, specific inhibitors targeting MACC1 post-translational protein modifications, to restrict tumor growth and metastasis, are not identified so far." (PMID 34247190, 2021). "Nevertheless, it is not stated whether MACC1 controls the immunological characteristics of cancer cells while enhancing the metastatic ability of the tumor cells." (PMID 34577857, 2021). "Notably, the low expression of c-Met in tumor tissues did not affect the regulation of MACC1 on endothelial cell angiogenesis, a critical process for cancer progression." (PMID 33425885, 2020). "It is not known, why MACC1 expression increases during tumor development." (PMID 32670264, 2020). "Moreover, tumor-excreted circ-PDE8A could be released into blood circulation by exosome transportation, acting as a ceRNA for miR-338 to regulate MACC1 and promote invasive metastasis through the MACC/MET/ERK or AKT pathways." (PMID 31277663, 2019). "However, no impact of MACC1 expression in the tumor center on the frequency of distant metastasis or patient survival was observed." (PMID 25884643, 2015). "As MACC1 has been suggested as a potential therapeutic target, overexpression on EMT-like cancer cells may represent an attractive option to manipulate cancer initiating cells at the tumor host interface in the process of invasion." (PMID 25884643, 2015). "No impact of MACC1 expression in tumor buds on survival was observed." (PMID 25884643, 2015). "In another group of HCC patients whose survival has been difficult to predict in the clinic, namely, those with tumor sizes smaller than 3 cm in diameter, the 5-year survival rate was 40% in the low MACC1 group, as opposed to 15% for patients exhibiting high MACC1 expression (P = 0.002)." (PMID 23717574, 2013). "To evaluate the diagnostic value of circulating MACC1 transcripts in plasma, we compared newly diagnosed CRC patients with a primary tumor with or without synchronous metastases (n = 71) with tumor-free volunteers (n = 54) and calculated sensitivity and specificity with a fourfold table." (PMID 23166620, 2012). "Notably, an impact of MACC1 on tumor cell/platelet communication has not been addressed yet." (PMID 34830078, 2021). "Moreover, MACC1 could also facilitate immune escape of tumors as it downregulates the expression of activated receptor NKG2D in NK cells by up-regulating TGF-β1, thus inhibiting the killing activity of NK cells, and facilitating tumor immune evasion." (PMID 34577857, 2021). "Therefore, MACC1 as a transcriptional factor could transcriptionally modulate endothelium-dependent angiogenesis and mediate TWIST1 upregulation, which is responsible for the angiogenesis and tumor progression of GC." (PMID 27280289, 2016). "For the following in vivo experiments, we used the SW620 cells with high endogenous MACC1 expression treated with and without shGIPC1 RNA in order to prove for the effects of GIPC1 silencing on tumor growth and metastasis formation in xenografted mice." (PMID 38144523, 2023). "Since MACC1 expression in SW480 cells or in xenograft tumours is not elevated upon S100P expression, the higher metastasis formation of SW480/S100P tumours is solely a consequence of S100P overexpression in these cells." (PMID 35597866, 2022). "In contrast to MACC1 expression, MEK1 expression is not prognostic for occurrence of later metastasis, and is independent of tumor stage." (PMID 34247190, 2021).
tumor (continued). "Second, the study was retrospective and we only verified the correlation between PET parameters and tumor markers in tissue level, biochemical measurement of GLUT-1 and MACC1 makers was not performed due to lack of serum samples." (PMID 33750337, 2021). "Cores with representative tumor material and evaluable staining were available in 266 of 360 samples (73.9%), with 211 samples (79.3%) being MACC1-positive (samples with IRS > 5) and 55 samples (20.7%) being MACC1-negative (samples with IRS < 5)." (PMID 35406545, 2022). "Finally, to assess if MEK1 is available in tumor tissue, we used the cohort of CRC patients from the initial discovery of MACC1 for MEK1 expression analysis as well as samples from normal mucosa." (PMID 34247190, 2021). "Thus, MEK1 is readily available in patient samples driving proliferation of tumor tissue, but expression level of the kinase MEK1 is not as important as that of its substrate MACC1 to force cancer cells to metastatic behavior." (PMID 34247190, 2021).
cancer (119 papers, 2011 to 2025). A tumor composed of atypical neoplastic, often pleomorphic cells that invade other tissues. "Colon cancer metastasis-associated protein 1 (MACC1) was initially identified in colorectal cancer and is linked to metastasis and prognosis in various malignant neoplasms." (PMID 41239615, 2025). "In GC, ACh drives migration via the M3R/AMP‐activated protein kinase (AMPK)/metastasis‐associated in colon cancer‐1 (MACC1) pathway, which is inhibited by MACC1 knockdown or darifenacin." (PMID 41415714, 2025). "Taken together, this study indicates that the metastasis inducer MACC1 acts as a cancer stem cell-associated marker." (PMID 38339354, 2024). "Metastasis-associated in colon cancer 1 (MACC1) was original identified as a transcription factor of c-MET, which activates the HGF/Met signal pathway and induces colon cancer cell metastasis and invasion." (PMID 39695175, 2024). "This study indicates that the metastasis inducer MACC1 acts not only as a cancer stem cell-associated marker, but also as a regulator of LGR5 expression and LGR5-mediated stem cell properties." (PMID 38339354, 2024). "Arlt and Stein were the first to identify metastasis-associated in colon cancer-1 (MACC1) as a prognostic biomarker of cancer invasion and metastasis in human colon cancer tissue, metastatic site tissue and normal tissue." (PMID 39544485, 2024). "Metastasis-associated colon cancer-1 (MACC1), a gene associated with tumor metastasis, plays a pivotal role in the development of cancer, although its specific functions and mechanisms in ESCC remain elusive." (PMID 38474224, 2024). "Metastasis-associated in colon cancer 1 (MACC1) is a prognostic and predictive biomarker that is now recognized in more than 20 cancer entities." (PMID 38611008, 2024). "Although MACC1 can already be linked with many hallmarks of cancer, one key process—the facilitation of immune evasion—remains poorly understood." (PMID 38611008, 2024). "Here, we focus on the cancer- and metastasis-inducing gene Metastasis-associated in colon cancer 1 (MACC1)." (PMID 38144523, 2023). "Metastasis associated in colon cancer 1 (MACC1) has been shown to be involved in the progression of more than 20 different types of cancer, including breast cancer, and performs specific functions in different cancers." (PMID 36979146, 2023). "MiR-23b targets metastasis-associated in colon cancer-1 (MACC1) inhibiting EC cells proliferation, invasion, and migration." (PMID 36335210, 2022). "Metastasis-associated with colon cancer protein 1 (MACC1) has been proven to play a critical role in cancer metastasis." (PMID 36333284, 2022). "One of the remarkable biomarkers, metastasis-associated in colon cancer 1 (MACC1), was discovered in 2009." (PMID 36432477, 2022). "Two important effects associated with increased MACC1 expression are increased cell migration and proliferation, both being hallmarks of cancer." (PMID 35740524, 2022). "The subgroup analysis stratified by the country, sample size, cancer type, detection method and analysis model of OS confirmed the significant association between the expression of MACC1 and OS." (PMID 33663046, 2021). "Metastasis-associated colon cancer gene-1 (MACC1) was first described as a c-MET transcription regulator that mediates cancer colon progression and metastasis by its ligand hepatocyte growth factor (HGF)." (PMID 34577857, 2021). "The activation of the PI3K pathway also upregulates the factor known as metastasis-associated in colon cancer 1 (MACC1), which promotes the Warburg effect in cancer cells, resulting in a poor prognosis." (PMID 34068319, 2021). "Here we deciphered the impact of tyrosine phosphorylation of MACC1, a causative driver for cancer metastasis, for cancer cell signaling and novel interventions to restrict cancer metastasis." (PMID 34247190, 2021). "MACC1 has been implicated in cancer malignancy and poor disease prognosis in several cancer types, and its downregulation was found to reduce tumorigenicity." (PMID 33854976, 2021).